FABP4 (fatty acid binding protein 4)
Diseases named in the same sentence as FABP4 in open-access papers (continued):
Sharing a sentence is not in itself a finding about the gene and the disease.
tumor (continued). "Notably, FABP4 levels in tumour tissues are inversely related to E-cadherin expression and positively associated with Snail protein levels as shown in IHC studies, suggesting a role in promoting EMT and tumour progression." (PMID 41154605, 2025). "As FABP4-positive tumor cells were mainly located in regions that often interacted with adipose tissue, we further determined whether FABP4 expression at the tumor/adipose tissue border impacted clinical parameters." (PMID 40106183, 2025). "However, invasive tumor cells near adipose tissue often express FABP4, suggesting that its presence in tumor cells may be ectopically acquired from neighboring adipocytes." (PMID 40106183, 2025). "None of these clinical parameters showed a significant correlation with FABP4 expression in tumors except the Elston-Ellis grade, which showed a weak but significant correlation with FABP4 H-score (Grade 1: 3.22 ± 4.69; Grade 2: 6.27 ± 10.99; Grade 3: 15.13 ± 28.1) in tumor cells." (PMID 40106183, 2025). "However, the mechanisms by which FABP4/FA complexes secreted from TAMs interact with tumor cells and mediate tumor metastasis remain unknown." (PMID 39513934, 2024). "Moreover, E0771 tumor size and weight in V9-treated mice were similar to those in FABP4−/− mice." (PMID 39054536, 2024). "Additionally, FABP4+ Mφ showed higher abundance in adjacent non‐tumour tissues than in tumour tissues from MPLCs and SPLCs, suggesting a potential role for FABP4+ Mφ in maintaining tissue homeostasis or exerting anti‐tumour effects in the adjacent non‐tumour tissue microenvironment." (PMID 39601163, 2024). "In addition, FABP4 expression was influenced by tumor stromal score and Lauren subtype." (PMID 37874427, 2024). "The hypothesis underpinning our study was that higher FABP-4 may be positively associated with CRC risk, which could be biologically explained by facilitating tumor growth via increased fatty acid supply, or FABP-4-related enhancement of inflammation and insulin resistance." (PMID 37833736, 2023). "Here, we investigated the association between FABP-4 concentrations measured in baseline blood samples and subsequent risk of CRC using data from a nested case-control study in the European Prospective Investigation into Cancer and Nutrition (EPIC) cohort, stratified by sex and tumor location." (PMID 37833736, 2023). "Moreover, lipids arising from adipocytes have been demonstrated to increase tumor growth and invasiveness by increasing the expression of fatty acid binding protein 4 (FABP4, i.e. fatty acid chaperone that is involved in glucose and lipid metabolism), heme oxygenase 1 (HMOX) and IL-1β." (PMID 37182144, 2023). "FABP4-induced lipid droplet formation in cancer cells has been shown to provide a resource for survival under hypoxia and oxidative stress-induced ferroptosis, which might promote tumor recurrence." (PMID 38060103, 2023). "Thus, FABP4 serves as a tumor-promoting molecule in most cancer types, and may be a promising therapeutic target for cancer treatment." (PMID 35899119, 2022). "These tumour EVs contain miRNAs, including miR-214-3p, which support the formation of a more favourable microenvironment by upregulation of lipogenesis genes, such as fatty acid-binding protein 4 (FABP4), adiponectin, and peroxisome proliferator-activated receptor ɣ (PPARɣ)." (PMID 35334544, 2022). "In addition, combination of FABP4 inhibitors with anti-tumor drugs like chemotherapy and TKIs could augment the anti-tumor effect of traditional." (PMID 35899119, 2022). "SCD1 and FABP4 could drive ferroptosis, thereby leading to tumor resistance." (PMID 35603151, 2022). "Therefore, we considered that FABP4 is low-expressed in various malignant tumors compared with normal tissues, but it may be upregulated during tumor development and metastasis and affect various metabolic pathways to promote cancer metastasis." (PMID 36532833, 2022).
tumor (continued). "We have previously shown that fatty acid-binding protein 4 (FABP4) was significantly upregulated following AnxA6 downregulation in BT-549 cells, and that this was consistent with increased cell proliferation and early onset and rapid xenograft tumor growth in mice." (PMID 35267416, 2022). "Importantly, FABP4 was correlated with the tumor size, recurrence-free survival and OS." (PMID 35899119, 2022). "However, the roles of FABP4 in NB and its effects on NB tumor cells are still unclear." (PMID 33931964, 2021). "Notably, intracellular FABP4 has been observed to enhance pro-tumour macrophage function." (PMID 34572888, 2021). "Therefore, the aim of our study was to detect the expression of FABP4 protein in GIST tumor samples, analyze the relationship between FABP4 expression level and clinicopathological features of patients with GISTs, and further analyzed the effect of FABP4 protein expression on the prognosis of GIST." (PMID 34558731, 2021). "Furthermore, inhibition of the LPL/FABP4/CPT1 axis could effectively delay the tumor growth in STAM mice." (PMID 34803493, 2021). "Induction of FABP4 expression may prevent tumor progression." (PMID 34943506, 2021). "In addition, FABP4 tumor endothelial cell immunostaining was significantly lower in mice treated with BMS309403 both in the preventive group (11.3%, ranges 8.6–22.2, p = 0.02) and in the curative group (0.1%, ranges 0.09–4.5, p = 0.007) than in controls (45.9%, ranges 44.6–77.6)." (PMID 30575815, 2019). "Moreover, overexpression of FABP4 led to inhibit tumor growth and decreased tumor volume in vivo." (PMID 29733540, 2018). "Moreover, multivariate Cox regression analysis indicated that the expression of FABP4, Alb, AFP, HBsAg, and PVTT were independent risk factors for overall survival, and the expression of FABP4, AFP, GGT, tumor size, and encapsulation were independent risk factors for HCC recurrence." (PMID 29733540, 2018). "Indeed, in the stromal regions of the primary tumour, the vascular expression of cleaved NOTCH1 (NOTCH1 intracellular domain, NICD, indicates active NOTCH1 signalling) correlated with FABP4 expression, whereas in vessels within the tumour and the tumour–stroma interface this correlation was lost." (PMID 27568980, 2017). "Thus increased hypoxia in combined BEV and DBZ-treated tumours in vivo may be contributing to reduced FABP4 expression." (PMID 27568980, 2017). "Although some of these data were not evaluated by statistical analysis, the results suggest that FABP4 secreted by some PCa cells may stimulate surrounding prostate stromal cells to produce proinflammatory cytokines in the prostate stromal tumor microenvironment." (PMID 29340091, 2017). "Furthermore, high expression of FABP3 or FABP4 in NSCLC was significantly associated with advanced tumor node metastasis (TNM) stage and had a negative impact on the overall survival of NSCLC patients." (PMID 27323829, 2016). "In order to test the hypothesis that the rs1054135 genotype facilitates tumour metastasis by regulating FABP4 expression, its protein expression was analyzed by immunohistochemistry in 52 TNBC tissues (disease-free group, n=34; relapsed group, n=18) with the associated genotype data." (PMID 26959740, 2016). "In addition, we provide results suggestive of bi-directional interaction between FABP4 and PPARγ pathways that may be driving aggressive tumor cell behavior in bone." (PMID 24240026, 2013). "In vivo, tumour growth was significantly reduced in FABP4 knockout mice, indicating that host-derived FABP4 supports PDAC tumour development." (PMID 41149452, 2025). "A significant down-regulation of CD36, FABP4, PLIN1, SCD5 and ACSL4 in tumor samples has also been validated by RT-qPCR." (PMID 40860798, 2025). "In obese TNBC patients, FABP4 upregulates ANGPTL4 and CD36, enhancing tumor angiogenesis and chemoresistance." (PMID 40717587, 2025). "FABP4 mediates the NLRP3/IL-1β pathway, inducing pyroptosis in macrophages and promoting tumor metastasis." (PMID 40717587, 2025).
tumor (continued). "Specifically, we observed a significant down-regulation of some of the most relevant genes in the PPAR pathway (CD36, FABP4, PLIN1, PLIN4, SCD5 and ACSL4) in tumor tissue samples." (PMID 40860798, 2025). "Lipid transfer from adipocytes to tumor cells occurs via FATPs, CD36, and FABP4, as previously reported." (PMID 40616161, 2025). "This complex activates and regulates downstream lipogenic factors, such as fatty acid-binding protein 4 (FABP4), FASN, and ACC, enhancing the ability of tumor cells to synthesize fatty acids." (PMID 40830338, 2025). "In LUAD studies, WGCNA combined with immune-related genes identified four key hub genes: CBLC, FABP4, GDF10, and LTBP4, showing significant differential expression between tumor and normal samples." (PMID 40766337, 2025). "In CRC, FABP4, together with CD36 and SCD, mediates fatty acid uptake in tumor cells, promoting liver and lung metastasis." (PMID 40717587, 2025). "In this study, FABP4, PPARGC1A, AGPAT4, ALDH1A1, and GPAT3 were identified as downregulated tumor suppressor genes in TC, whereas TGFA was recognized as an oncogene." (PMID 40119647, 2025). "In vivo, the FABP4 inhibitor BMS309403, either alone or in combination with cetuximab, significantly reduced tumor growth in resistant CRC models, highlighting its therapeutic potential." (PMID 39823981, 2025). "Specifically, CD36, FABP4, PLIN1, SCD5 and ACSL4 were significantly downregulated in tumor samples (p < 0.05)." (PMID 40860798, 2025). "We compared the tumor metabolites between the TRAMP-HF and FABP4−/− TRAMP-HF mice, and found that nine essential and ten non-essential amino acids (excluding Cys) were 1.3–3.6-fold lower in the FABP4−/− TRAMP-HF group than in the TRAMP-HF group." (PMID 41226657, 2025). "The fatty acid binding protein-4 (FABP4) inhibitor can inhibit TME lipid transport and reduce tumor regeneration." (PMID 40002387, 2025). "We developed a monoclonal neutralizing antibody that specifically targets FABP4, which not only efficiently blocked FABP4-driven CSC functions, but also efficiently suppressed tumor formation in a MASLD-HCC mouse model." (PMID 41392988, 2025). "CAFs highly express fatty acid-binding protein 4 (FABP4), which specifically binds long-chain fatty acids and enhances their transmembrane transport, significantly increasing lipid accumulation in tumor and stromal cells." (PMID 40563359, 2025). "High expression of FABP4, along with CD36 and perilipin 2, facilitates lipid transfer from BMAT to tumor cells." (PMID 40852589, 2025). "Another study analyzed tumor specimens from 246 CRC patients and identified fatty acid binding protein 4 (FABP4) expression in 37.0% of CRCs." (PMID 39113889, 2024). "Given the protumor role of lipid accumulation in TAMs, we treated FABP4 WT or KO macrophages with PA, LA, or BSA, and evaluated their protumor function using trans-well tumor migration assays." (PMID 39513934, 2024). "While FABP4 expression was comparable between the groups, we observed higher expression levels of CD36 and ANGPTL4 in tumor cells at the invasive front in overweight/obese TNBC patients." (PMID 39456610, 2024). "Similarly to the presence of TAF and SARIFA-positivity, upregulation of CD36 and FABP4 is associated with worse outcomes in univariate Kaplan-Meier analysis in TCGA-CRC regarding most endpoints, strengthening the association between an increased lipid metabolism and an aggressive tumor behavior." (PMID 39147895, 2024). "Tumor resistance to ferroptosis, which is driven by SCD1 in cancer cells or by fatty acid binding protein-4 (FABP4) in the tumor microenvironment, promotes tumor recurrence." (PMID 38383297, 2024). "Consistent with Prayugo’s analysis results, recent studies have shown that FABP4 is more expressed in tumor node metastasis stages I-II than III-IV and is involved in metabolic reprogramming, tumor differentiation, and metastasis." (PMID 39103344, 2024).
tumor (continued). "Pharmacological inhibitors of FABP4, such as tamoxifen and BMS309403, effectively inhibit tumor progression." (PMID 37545500, 2023). "In terms of exploring residual disease-related biomarkers, Anil K. Sood found that FABP4 and ADH1B were highly expressed in the tumor tissue of non-R0 patients." (PMID 38129848, 2023). "FABP4 inhibitor BMS309403, was also found to boost the efficacy of carboplatin by inhibiting tumor metastasis in in vivo ovarian cancer models." (PMID 37700339, 2023). "We also screened out two potential key genes FABP4 and VWF related to tumor microenvironment using transcriptome sequencing, follow-up information and biomedical literature data, which were validated by laboratory experiments." (PMID 37950277, 2023). "Strong positive correlations were found between CD31 levels in primary tumor tissue and FABP4+MMP9+MMP2+TIMP1- (r = 0.82, p < 0.05) and FABP4+MMP9+MMP2-TIMP1- (r = 0.67, p < 0.05) populations of plasma sEVs." (PMID 37109070, 2023). "Then, the released fatty acids are promptly uptaken by cancer cells, which upregulate fatty acid-binding protein 4 (FABP4) in omental metastases, to generate energy by β-oxidation and meet the increasing demand of the rapid tumor growth." (PMID 35328686, 2022). "The blockade of FABP4 and SCD1 activity in tumors inhibited these processes and significantly reduced tumor recurrence (Wan, Guo, Zhu, & Qu, 2020)." (PMID 35646090, 2022). "Some investigators found that FABP4 inhibited HCC cell proliferation and invasion in vitro while leading to the inhibition of tumor growth and reduction in tumor size in vivo." (PMID 36532833, 2022). "No mutations in catechol-O-methyltransferase (COMT), fatty acid binding protein 4 (FABP4), myoglobin (MB) and metallothionein 2A (MT2A) were detected in COAD tumor tissues." (PMID 36203457, 2022). "SPINK1, FABP4, and MMP10 showed darker staining in tumor tissues, and GPRASP1, CLCA4, and LAMP5 showed lighter staining." (PMID 35479956, 2022). "FABP4 and FABP5 knockdown in GC cells significantly boosted lipid uptake in tissue-resident memory T cells (TRM) in a tumor cell–T cell co-culture system when compared to FABP4 or FABP5 knockdown alone." (PMID 35625633, 2022). "We also found that ARL4C and HOXC8 were upregulated, and FABP4, PCOLCE2, SERPING1, and SRPX were downregulated in tumor tissue compared to corresponding healthy tissue." (PMID 35664768, 2022). "The administration of this natural product inhibited tumor growth by downregulating PPARα, PPARγ, FABP1, FABP4, and FABP5." (PMID 36296934, 2022). "While FABP4 acts as a tumor suppressor when ectopically expressed in DU145 PCa cells, recent studies suggest FABP4 involvement in adipose-PCa crosstalk." (PMID 34386430, 2021). "Upregulated FABP4 in both AML cells and adipocytes was observed when they were in co-culture, which increased tumor cell proliferation, as validated by short hairpin RNA knockdown experiments." (PMID 33498240, 2021). "The results indicated that FABP4, ERMN, and CHST11 were overexpressed in CRC tumor tissues compared with normal tissues." (PMID 34294834, 2021). "We further verified the potential for CD36 and FABP4 inhibitors (SSO and BMS309403, respectively) to suppress tumour growth through in vivo xenograft nude mice models." (PMID 34561446, 2021). "By quantitatively analyzing and comparing the number and volume of tumor masses formed at 20 weeks, LPL, FABP4 or CPT1 inhibitors significantly reduced liver carcinogenesis in STAM mice, especially in the Orlistat group and BMS309403 group." (PMID 34803493, 2021). "Primarily expressed in the adipocytes and macrophages, fatty acid binding protein 4 (FABP4) is involved in lipid transfer between adipocytes and tumor cells, provoking the fatty acid oxidation to induce tumor growth." (PMID 34898475, 2021). "Most tumor cells presented cytoplasmic and/or membranous staining patterns, except for VAP1, FABP4, PF4, and AGP, which occasionally displayed focal nuclear staining." (PMID 32224886, 2020).
tumor (continued). "We also show that specific inhibitors of FABP4 and FABP5 and the plant-derived galactolipid, dLGG, inhibit the metastatic phenotype in TNBC cells and in tumor inoculated animals." (PMID 31941087, 2020). "We then examined the levels of Ki67, FABP4, FABP5, and CYP2C19 in tumor and lung tissues by IHC staining." (PMID 31941087, 2020). "In a separate study, artificial amplification of HER2 cDNA in a non-tumor breast epithelial cell line, HB4a, forced the upregulation of lipogenic fatty acid translocase (CD36), fatty acid-binding protein 4 (FABP4) and FASN expression." (PMID 32872164, 2020). "Whilst metformin treatment reduced FABP4 upregulation in vitro, specific FABP4 inhibitor BMS309403 reduced tumour growth in vivo in murine xenograft models." (PMID 32982772, 2020). "Our investigations identified three major invasiveness biomarkers common to the three tumor sources, CAPG, FABP4, and LAMB2, and an additional set of 25 candidate biomarkers shared by rat and patient tumors." (PMID 32867073, 2020). "Higher levels of fatty acid-binding protein 4 (FABP4) are found in the omental metastases in comparison with the cells from the primary tumors, a protein that was also found at the adipocyte–tumor cell interface." (PMID 32354024, 2020). "FABP4 and CD36 are the main lipid transporters during the interaction of tumour cells and adipocytes." (PMID 31334678, 2019). "Western blot revealed that the protein expressions of FABP4 and FABP6 were significantly higher in tumor tissues than in adjacent tissues (P < 0.001, P = 0.002, respectively)." (PMID 31651326, 2019). "Western blot revealed that the protein expressions of FABP4 and FABP6 were significantly higher in tumor tissues than in adjacent tissues." (PMID 31651326, 2019). "We then stained the tumor sections taken from these mice with CA9 (a hypoxia marker) and FABP4; we observed co-localization of FABP4 with CA9." (PMID 30050129, 2018). "Designing highly selective inhibitors of fatty acid binding proteins 4 and 5 (FABP4 and FABP5) is of importance for treatment of some diseases related with inflammation, metabolism, and tumor growth." (PMID 30142969, 2018). "The univariate analysis revealed that the AST, AFP, GGT, ALP, PVTT, tumor size, micro metastasis, encapsulation, MVI, BCLC, and FABP4 expression were correlated with RFS of HCC patients." (PMID 29733540, 2018). "We found that low FABP4 expression was significantly correlated with Alb (P = 0.038), AFP level (P = 0.007), CA19‐9 (P = 0.048), PVTT (P = 0.016), tumor size (P = 0.018), and encapsulation (P = 0.022)." (PMID 29733540, 2018). "And we the Alb, AST, AFP, GGT, HBsAg, PVTT, number of tumor, micro metastasis, encapsulation, MVI, BCLC, FABP4 expression were correlated with OS of HCC patients." (PMID 29733540, 2018). "Previously we have shown that FABP4 in endothelial cells is induced by the NOTCH1 signalling pathway, the latter of which is involved in mechanisms of resistance to antiangiogenic tumour therapy." (PMID 27568980, 2017). "Given that FABP4 is a significant medium of fuel supply for tumour growth, and probably involved in tumour angiogenesis, the rs1054135 SNP located in the 3′-UTR of FABP4 may influence patient susceptibility to TNBC recurrence through posttranscriptional regulation of FABP4 expression." (PMID 26959740, 2016). "The expression of PLIN1 (p < 0.001), FABP4 (p = 0.029), CPT-1A (p = 0.001), ACOX-1 (p < 0.001), and FASN (p < 0.001) differed significantly among these tumor subtypes." (PMID 25751270, 2015). "Further investigations into adipocyte-driven FABP4, HMOX-1 and IL-1β expression in tumor cells revealed that transcriptional upregulation of these factors in vitro correlates with increased protein levels." (PMID 24240026, 2013).